MATCAP2 (microtubule associated tyrosine carboxypeptidase 2)
Description:
Putative tyrosine carboxypeptidase.
Synonyms: KIAA0895; TMCP2
Tractability: Antibody: the Human Protein Atlas places it where antibodies can reach. PROTAC: ubiquitination databases record sites on it.
Gene: Protein-coding gene on chromosome 7 (36,324,152 to 36,390,125, reverse strand). Ensembl gene ENSG00000164542.
Subcellular location (Human Protein Atlas): Nucleoplasm; Cell Junctions; Cytosol; Plasma membrane
Genetic constraint (gnomAD): Loss-of-function variants: 32 observed, 46.8 expected, observed/expected ratio (o/e) 0.68, 90% interval 0.51 to 0.92. The upper end of that interval is the gene's LOEUF score, 0.92, which puts it in group 3 of 6, group 1 being the genes least tolerant of losing a copy. Missense variants: 477 observed, 594.56 expected, observed/expected ratio (o/e) 0.8, 90% interval 0.74 to 0.87. Synonymous variants: 181 observed, 210.32 expected, observed/expected ratio (o/e) 0.86, 90% interval 0.76 to 0.97.
Homologues: Orthologues: macaque MATCAP2 (97% identical), dog MATCAP2 (93% identical), guinea pig MATCAP2 (90% identical), chimpanzee MATCAP2 (89% identical), rabbit MATCAP2 (89% identical), rat Matcap2 (88% identical), mouse Matcap2 (86% identical), pig MATCAP2 (85% identical), tropical clawed frog matcap2 (63% identical), zebrafish matcap2 (59% identical). Paralogues in human: MATCAP1 (43% identical).
Diseases named in the same sentence as MATCAP2 in open-access papers:
MATCAP2 is named in the same sentence as 2 diseases in open-access papers, as found by Europe PMC text mining. Sharing a sentence is not in itself a finding about the gene and the disease.
MATCAP2 shares sentences with these, for which no sentence is quoted: infection (1 paper); tumor (1).